WDR3 (WD repeat domain 3)
Description:
Part of the small subunit (SSU) processome, first precursor of the small eukaryotic ribosomal subunit. During the assembly of the SSU processome in the nucleolus, many ribosome biogenesis factors, an RNA chaperone and ribosomal proteins associate with the nascent pre-rRNA and work in concert to generate RNA folding, modifications, rearrangements and cleavage as well as targeted degradation of pre-ribosomal RNA by the RNA exosome.
Synonyms: FLJ12796; UTP12; DIP2
Tractability: Small molecule: a structure with a bound ligand is known. PROTAC: UniProt records ubiquitination sites on it; ubiquitination databases record sites on it; its protein half-life has been measured.
Target class: Reader; Epigenetic regulator; Methyl-lysine/arginine binding protein; WDR domain
Gene: Protein-coding gene on chromosome 1 (117,929,063 to 117,966,543, forward strand). Ensembl gene ENSG00000065183.
Subcellular location: Nucleus, nucleolus
Subcellular location (Human Protein Atlas): Nucleoli; Nucleoplasm
Pathways (Reactome):
Metabolism of RNA: Major pathway of rRNA processing in the nucleolus and cytosol; rRNA modification in the nucleus and cytosol
Gene Ontology:
Molecular function: RNA binding; snoRNA binding
Biological process: ribosomal small subunit biogenesis; maturation of SSU-rRNA
Cellular component: nucleolus; nucleoplasm; small-subunit processome; Pwp2p-containing subcomplex of 90S preribosome
Genetic constraint (gnomAD): Loss-of-function variants: 77 observed, 119.47 expected, observed/expected ratio (o/e) 0.64, 90% interval 0.54 to 0.78. The upper end of that interval is the gene's LOEUF score, 0.78, which puts it in group 3 of 6, group 1 being the genes least tolerant of losing a copy. Missense variants: 1,006 observed, 1,152 expected, observed/expected ratio (o/e) 0.87, 90% interval 0.83 to 0.92. Synonymous variants: 380 observed, 400.68 expected, observed/expected ratio (o/e) 0.95, 90% interval 0.87 to 1.03.
Homologues: Orthologues: chimpanzee WDR3 (99% identical), macaque WDR3 (98% identical), rabbit WDR3 (95% identical), pig WDR3 (94% identical), guinea pig WDR3 (94% identical), dog WDR3 (93% identical), mouse Wdr3 (91% identical), rat Wdr3 (90% identical), tropical clawed frog wdr3 (74% identical), zebrafish wdr3 (71% identical), Drosophila melanogaster CG8064 (42% identical). Paralogues in human: TBC1D31 (17% identical).
Diseases named in the same sentence as WDR3 in open-access papers:
WDR3 is named in the same sentence as 13 diseases in open-access papers, as found by Europe PMC text mining. Sharing a sentence is not in itself a finding about the gene and the disease. The quoted sentences say what the papers report.
pancreatic cancer (3 papers, 2021 to 2025). "However, the biological role of WDR3 in pancreatic cancer and the associated mechanism remains unclear." (PMID 33648545, 2021). "By interacting with GATA4, WDR3 activated the Hippo signaling pathway, demonstrating that it was crucial in promoting the advancement of pancreatic cancer." (PMID 38098990, 2023). "Our study proved that overexpressed WDR3 was correlated with poor survival in pancreatic cancer and that WDR3 silencing significantly inhibited the proliferation, invasion, and tumor growth of pancreatic cancer." (PMID 33648545, 2021). "In brief, all these data showed that WDR3 knockdown enhanced the anti-pancreatic cancer effect of YAP1 inhibition both in vitro and in vivo." (PMID 33648545, 2021). "We identified a novel mechanism by which WDR3 plays a critical role in promoting pancreatic cancer progression by activating the Hippo signaling pathway through the interaction with GATA4." (PMID 33648545, 2021). "Consistently, our results also indicated that overexpressed WDR3 increased the proliferation and invasion abilities of pancreatic cancer cells." (PMID 33648545, 2021). "Colony formation and MTS assays showed that WDR3 overexpression significantly promoted the proliferation of pancreatic cancer cells, while a transwell invasion assay proved that WDR3 overexpression increased the invasive ability of pancreatic cancer cells." (PMID 33648545, 2021). "Our study proved that overexpressed WDR3 was correlated with poor survival in pancreatic cancer and WDR3 silencing significantly inhibited the proliferation, invasion, and tumor growth of pancreatic cancer." (PMID 33648545, 2021). "Taken together, our results indicated that silenced WDR3 significantly inhibited the proliferation and invasion ability of pancreatic cancer cells in vitro and in vivo." (PMID 33648545, 2021). "In our study, we proved that overexpressed WDR3 was correlated with poor survival in pancreatic cancer patients." (PMID 33648545, 2021). "Consistently, GATA4 knockdown also reversed the inhibition of proliferation and invasion ability of pancreatic cancer cells induced by WDR3 silencing." (PMID 33648545, 2021). "The GEPIA web tool was searched, and IHC assays were conducted to determine the mRNA and protein expression levels of WDR3 in pancreatic cancer patients." (PMID 33648545, 2021). "Combined with the inhibition of YAP1 transcription induced by WDR3 knockdown, TED-347 treatment further enhanced the ability of WDR3 silencing to inhibit pancreatic cancer progression." (PMID 33648545, 2021). "Taken together, our results emphasize the importance of WDR3 as a therapeutic target in pancreatic cancer." (PMID 33648545, 2021). "We seek to explore the immune-independent functions and relevant mechanism for WDR3 in pancreatic cancer." (PMID 33648545, 2021). "Taken together, our results indicated that overexpressed WDR3 significantly promoted the proliferation and invasion ability of pancreatic cancer cells in vitro and in vivo." (PMID 33648545, 2021). "Colony formation and MTS assays showed that WDR3 inhibition significantly inhibited the proliferation of pancreatic cancer cells, while a transwell invasion assay proved that WDR3 inhibition decreased the invasive ability of pancreatic cancer cells." (PMID 33648545, 2021). "In our study, we first proved that WDR3 was overexpressed and positively correlated with poor survival in pancreatic cancer." (PMID 33648545, 2021). "However, the biological mechanism of WDR3 overexpression in pancreatic cancer still needs further study." (PMID 33648545, 2021). "Since WDR3 silencing could inhibit YAP1 expression at the mRNA and protein levels, we hypothesized that The WDR3 knockdown enhanced the anti-pancreatic cancer effect of YAP1 inhibition." (PMID 33648545, 2021). "Therefore, we concluded that WDR3 was significantly overexpressed and positively correlated with poor survival in pancreatic cancer." (PMID 33648545, 2021).
pancreatic cancer (continued). "Furthermore, by overexpressing YAP1 in WDR3 silenced PANC-1 cells, we found that overexpressed YAP1 reversed the inhibition of the proliferation and invasion ability in pancreatic cancer cells induced by WDR3 silencing." (PMID 33648545, 2021). "WDR3 silencing could inactivate the Hippo signaling pathway by decreasing YAP1 expression in pancreatic cancer cells." (PMID 33648545, 2021). "Therefore, the regulation of YAP1 by WDR3 was found to be dependent on GATA4 in pancreatic cancer cells." (PMID 33648545, 2021). "Finally, compared with normal pancreatic cells, pancreatic cancer cells expressed high levels of WDR3." (PMID 33648545, 2021). "Furthermore, the mRNA expression of CTGF and CYR61, the major downstream regulatory genes in the Hippo signaling pathway, was also positively correlated with the expression level of WDR3 in pancreatic cancer cells." (PMID 33648545, 2021). "We have proved that overexpressed WDR3 could increase the proliferation and invasion abilities of pancreatic cancer cells and was correlated with poor survival in pancreatic cancer patients." (PMID 33648545, 2021). "Therefore, we speculated that WDR3 plays an important biological role in the progression of pancreatic cancer." (PMID 33648545, 2021). "Therefore, WDR3 is potentially a therapeutic target for pancreatic cancer treatment." (PMID 33648545, 2021). "Furthermore, IHC analysis verified the overexpression of WDR3 in pancreatic cancer patients." (PMID 33648545, 2021). "Furthermore, WDR3 activated the Hippo signaling pathway by inducing yes association protein 1 (YAP1) expression, and the combination of WDR3 silencing and administration of the YAP1 inhibitor TED-347 had a synergistic inhibitory effect on the progression of pancreatic cancer." (PMID 33648545, 2021). "Consistently, the orthotopic syngeneic model of pancreatic cancer in C57BL/6 mice verified that the combined treatment of WDR3 silencing and TED-347 treatment further inhibited of tumor growth of pancreatic cancer." (PMID 33648545, 2021). "Silencing WDR3 significantly decreased the expression levels of YAP1 and the downstream target genes CTGF and CYR61 in pancreatic cancer." (PMID 33648545, 2021). "GATA4 knockdown reversed the inhibition of YAP1 and proliferation and invasion of abilities of pancreatic cancer cells induced by WDR3 silencing and reversed the upregulation of YAP1 expression induced by WDR3 overexpression." (PMID 33648545, 2021). "Consistently, the GEPIA searching result showed a positive correlation between WDR3 and YAP1 mRNA expression levels in pancreatic cancer patient specimens." (PMID 33648545, 2021). "Finally, the combination of WDR3 silencing and administration of the YAP1 inhibitor TED-347 had a synergistic inhibitory effect on the progression of pancreatic cancer." (PMID 33648545, 2021). "We demonstrated that WDR3 could regulate YAP1 expression in pancreatic cancer cells, but the clinical relationship between WDR3 and YAP1 in human pancreatic cancer specimens remains unclear." (PMID 33648545, 2021). "Besides, MTS and colony formation assays indicated the synergistic effect of WDR3 silencing and TED-347 treatment, demonstrating inhibition of the proliferative ability of pancreatic cancer cells in vitro." (PMID 33648545, 2021). "Therefore, all these results suggested a positive correlation between the expression levels of WDR3 and YAP1 in pancreatic cancer specimens." (PMID 33648545, 2021). "Interestingly, our results identified a protein interaction between WDR3 and GATA4 that led to the regulation of GATA4 nuclear translocation and YAP1 expression in pancreatic cancer." (PMID 33648545, 2021). "Furthermore, WDR3 induced YAP1 expression by interacting with GATA4 and inducing the nuclear translocation of GATA4, the transcription factor of YAP1, in pancreatic cancer cells." (PMID 33648545, 2021).
pancreatic cancer (continued). "Finally, the upregulation of YAP1 expression induced by WDR3 was dependent on an interaction with GATA binding protein 4 (GATA4), the transcription factor of YAP1, which interaction induced the nuclear translocation of GATA4 in pancreatic cancer cells." (PMID 33648545, 2021). "Furthermore, WDR3 silencing could significantly decrease the proliferative and invasive abilities of pancreatic cancer cells by inducing YAP1 inhibition, which was found to rely on the interaction between WDR3 and GATA4." (PMID 33648545, 2021). "Moreover, survival rate analysis results indicated that the elevated expression level of WDR3 was correlated with poor disease-free survival (DFS) and overall survival (OS) in pancreatic cancer, rather than other malignant cancers." (PMID 33648545, 2021).
thyroid cancer (3 papers, 2012 to 2025). "In thyroid cancer, WDR3 maintains genomic stability in patients, while its location on the 1p12 chromosome contributes to the disease susceptibility." (PMID 40646517, 2025). "Previous studies conducted by our group in this region have found that the WDR3 gene, mapped in this region, shows a significant association with DTC, suggesting its implication in the aetiology of thyroid cancer." (PMID 23049746, 2012). "Aiming to find a reasonable explanation for the association observed between WDR3 polymorphisms and DTC incidence, we have already reported the up-regulation of WRD3 in different thyroid cancer cell lines, suggesting its possible implication in thyroid cancer tumorigenesis." (PMID 23049746, 2012). "Since neither of the functions attributed to WDR3 can be specifically associated with thyroid cancer, we hypothesized that perhaps it is involved in more general mechanisms maintaining genomic stability." (PMID 23049746, 2012).
breast carcinoma (2 papers, 2012 to 2023). "This would agree with the studies carried out in the breast carcinoma cell line MCF-7 showing that the suppression of WDR3 reduce cell proliferation, decrease cell size and reduce foci formation, indicating that WDR3 confers a growth and proliferative advantage on cancer cells." (PMID 23049746, 2012).
chronic heart failure (1 paper, 2025). "Importantly, Wdr3 is involved in the Hippo signalling pathway, and we previously reported that the Hippo pathway is a regulator of Bim expression in a chronic heart failure model." (PMID 40759792, 2025).
colon cancer (1 paper, 2012). "Interesting, preliminary results with colon cancer patients (V. Moreno, personal communication) seem to indicate an altered expression of WDR3 in colon cancer, supporting our view, proposing a role of WDR3 in genomic stability and cancer." (PMID 23049746, 2012).
differentiated thyroid carcinoma (1 paper, 2012). Differentiated thyroid carcinoma (DTC), also known as papillary or follicular thyroid carcinoma, is a slow-growing malignancy usually presenting in adults as an asymptomatic thyroid mass. "The role of the WDR3 gene on genomic instability has been evaluated in a group of 115 differentiated thyroid cancer (DTC) patients." (PMID 23049746, 2012).
Infertility (1 paper, 2021). "Of interest, some candidates related to sperm and infertility were identified, containing MORC1, TDRD9, ZFYVE21, ADGRB3, SPAG17, CKB, and WDR3, which may have effects on sperm motility and fertilization." (PMID 33477586, 2021).
osteosarcoma (1 paper, 2025). A usually aggressive malignant bone-forming mesenchymal neoplasm, predominantly affecting adolescents and young adults. "Among them, WDR3 was a prognostic risk factor for osteosarcoma and stably bound to Nilotinib in the molecular docking model." (PMID 40646517, 2025). "WDR3 not only serves as a prognostic risk factor for osteosarcoma, but is also highly expressed in U2-OS cells." (PMID 40646517, 2025). "Among them, WDR3 emerged as a prognostic risk factor for osteosarcoma and bound stably to Nilotinib in molecular docking models." (PMID 40646517, 2025). "In addition, WDR3 could form droplets, and its IDR mutation eliminated phase-separated levels of WDR3, thereby ameliorating the aggressive phenotype of osteosarcoma cells." (PMID 40646517, 2025). "Therefore, disruption of WDR3 phase separation is closely associated with mast cell-mediated inflammatory responses, thus affecting the mechanisms of metastasis and drug resistance in osteosarcoma." (PMID 40646517, 2025). "Therefore, we speculated that WDR3 phase separation-mediated tumorigenesis in osteosarcoma may be associated with the coordinated regulation of SNRPB expression and lysosomal degradation pathways." (PMID 40646517, 2025). "Although the role of WDR3 in osteosarcoma remains unexplored, it has been found to promote cancer stem cell characteristics by inhibiting USF2-mediated RASSF1A transcription." (PMID 40646517, 2025). "Considering the binding stability of WDR3 to Nilotinib, this study focused on exploring the impact of WDR3 phase separation on osteosarcoma and its involvement in Nilotinib-based antitumor therapy." (PMID 40646517, 2025). "Functionally, WDR3 was significantly overexpressed in osteosarcoma cells, whereas its downregulation inhibited the malignant progression of osteosarcoma both in vivo and in vitro." (PMID 40646517, 2025). "First, we used lentiviral transfection to specifically down-regulate WDR3 expression in U2-OS cells to observe its effect on osteosarcoma progression in vitro and in vivo." (PMID 40646517, 2025). "The animal experiments were also carried out to confirm the role of WDR3 phase separation in the Nilotinib-based treatment for osteosarcoma." (PMID 40646517, 2025). "In transfected U2-OS cells and xenograft mice, the downregulation of WDR3 significantly inhibited the malignant progression of osteosarcoma." (PMID 40646517, 2025). "Regarding therapeutic implications, WDR3 bound stably to Nilotinib in this study and mediated the therapeutic mechanism of Nilotinib against osteosarcoma." (PMID 40646517, 2025). "Functional experiments have shown that the knockdown of WDR3 inhibited the proliferation and metastatic ability of osteosarcoma cells while suppressing tumor growth." (PMID 40646517, 2025). "Moreover, the treatment with Nilotinib improved the progression of osteosarcoma in vivo and in vitro, while inhibiting the production of WDR3 phase-separated condensates." (PMID 40646517, 2025). "More importantly, WDR3 can form condensates with liquid-like behavior in U2-OS cells, and mutation of its IDR can eliminate the phase-separated level of WDR, thus reversing the aggressive phenotype of osteosarcoma cells." (PMID 40646517, 2025). "Furthermore, WDR3 expression was positively correlated with the infiltration level of activated mast cells in osteosarcoma." (PMID 40646517, 2025). "Therefore, Nilotinib may alleviate the progression of osteosarcoma in vivo and in vitro by inhibiting the phase separation of WDR3." (PMID 40646517, 2025). "Thus, silencing of WDR3 can effectively alleviate the malignant progression of osteosarcoma." (PMID 40646517, 2025). "Thus, the phase separation of WDR3 could promote the proliferation, migration, and invasion of osteosarcoma in vitro." (PMID 40646517, 2025). "WDR3 phase separation involves in the therapeutic mechanism of Nilotinib against osteosarcoma, and thus may serve as a potent biomarker to ameliorate adverse events following osteosarcoma treatment." (PMID 40646517, 2025).
osteosarcoma (continued). "Moreover, the expression of WDR3 may affect the sensitivity of patients with osteosarcoma to drugs, such as AZD4547 and Nilotinib." (PMID 40646517, 2025). "In vivo, downregulation of WDR3 also significantly reduced the tumor volume and tumor weight in xenografted mice with osteosarcoma, without affecting their body weights." (PMID 40646517, 2025).
prostate carcinoma (1 paper, 2023). A carcinoma that arises from epithelial cells of the prostate gland. "Additionally, prostate cancer (PCa) tissues were found to have a substantially higher WDR3 level, and WDR3 overexpression increased markers of stem cell-like characteristics." (PMID 38098990, 2023).